TREM1 (triggering receptor expressed on myeloid cells 1)
Diseases named in the same sentence as TREM1 in open-access papers (continued):
Sharing a sentence is not in itself a finding about the gene and the disease.
infection (continued). "Following infection in both blood and spleen there was upregulation of canonical pathways including “Granulocyte Adhesion and Diapedesis”, “TREM1 Signaling” and “IL-10 Signaling”." (PMID 26918359, 2016). "The TREM-1-mediated innate immune response was confirmed to play an essential role in the activation of neutrophils, which further benefited the outcome of the infection by improving S. suis clearance." (PMID 26618144, 2015). "major promastigotes s.c. in the footpad of Trem1+/+ and Trem1−/− mice, an attenuation in lesion development was apparent in Trem1−/− mice already at 14 days post infection." (PMID 24453980, 2014). "There was a decrease in TREM-1 expression at both levels at 1 day post-infection (P<0.05), similar to the clinical score data." (PMID 25464008, 2014). "Trem1−/− mice also exhibited reduced neutrophilic infiltration and decreased lesion size upon infection with Leishmania major." (PMID 24453980, 2014). "We further analysed the cellular composition of infected footpads from Trem1−/− and Trem1+/+ mice at 21 days post infection." (PMID 24453980, 2014). "Another recent study by Suthar and co-workers used transcriptional profiling and pathway modeling to show that TREM-1 signaling was enriched in the liver following infection with WNV in mice." (PMID 25505454, 2014). "Paired samples of Bronchiolo-alveolar lavage fluid (BALF) and blood from each subject were analysed for putative biomarkers of infection: Cellular (TREM-1, CD11b and CD62L) and soluble (IL-1β, IL-6, IL-8, sTREM-1, Procalcitonin)." (PMID 25289689, 2014). "Intrigued by the substantially diminished inflammatory lesions, yet intact parasite clearance in L. major-infected Trem1−/− mice, we aimed to substantiate these findings in an altogether different infection model." (PMID 24453980, 2014). "It was found that both P. gingivalis gingipain-mutant strains induced TREM-1 expression in PMNs to a similar extent as their parental wild-type W50 strain, after 4 h of infection." (PMID 24124513, 2013). "Polymorphonuclear neutrophils (PMNs) are the first line of defence against infection, and a major source of TREM-1." (PMID 24124513, 2013). "Genes belonging to the TREM1 signaling pathway were found to be differentially regulated in the mouse lungs, most likely in infiltrating neutrophils, during the infection by the high and low virulence H3N2 viruses." (PMID 24073225, 2013). "The purpose of this study was to investigate the effect of corticosteroids on TREM-1 expression on neutrophils in a lethal mouse infection model, and to examine the stimulated expression of TREM-1 and on sTREM-1 on human myeloid cells in vitro." (PMID 24350219, 2013). "The presented mouse experiments further suggest that host fate can be determined within hours of infection by the differential activation (in target lung tissue) of genes in the IL-17 and TREM1 pathways." (PMID 24073225, 2013). "On the other hand complete silencing of Trem-1 via SI-RNA decreased bacterial clearance and increased mortality in a mouse model of infection." (PMID 23414215, 2013). "Taken together, the findings of these animal studies and results of the present study suggest that modulation of TREM-1 is a possible therapeutic target for acute infection settings." (PMID 24350219, 2013). "Soluble TREM-1 (sTREM-1) will be either secreted or shed under the condition of infection, and then sTREM-1 can be detected in BALF." (PMID 23734253, 2013). "Blockade of Trem-1 with antibodies or SI-RNA before or after endotoxin challenge in experimental murine infection influences the proinflammatory reaction." (PMID 23414215, 2013). "During infection, soluble TREM-1 (sTREM-1) is generated through proteolytic cleavage of the TREM-1 ectodomain by matrix metalloproteinases." (PMID 23468854, 2013). "Recently, soluble triggering receptor expressed on myeloid cells-1 (sTREM-1) appears to be a potential marker of infection." (PMID 23194114, 2012).
infection (continued). "TREM-1 amplifies infection-induced inflammatory response signals primarily through the mediation of adapter protein DAP12 on the cell surface." (PMID 23194114, 2012). "Results suggest that TREM-1 expression on the membranes of neutrophils and monocytes in patients with septic syndrome is related to the type of infection." (PMID 22050935, 2011). "Triggering receptor expressed on myeloid cells (TREM)-1 is a neutrophil and monocyte receptor up-regulated during infection." (PMID 20920231, 2010). "The aim of our present study was to measure the levels of TREM-1 and HLA-DR on monocytes, and the serum concentrations of IL-6 and IL-10 in patients with AP, and to determine whether these markers can be used for early identification of patients at high risk of developing severe AP or infection." (PMID 19442309, 2009). "Previous work from our laboratory indicated that soluble TREM-1 is generated after LPS challenge or pathogen infection via limited proteolysis of membrane-anchored receptor by LPS-activated matrix metalloproteinases." (PMID 18628981, 2008). "Tacrolimus may reduce corneal damage in the early stages of infection by downregulating TREM-1 expression." (PMID 41226426, 2025). "Furthermore, IL-23 p19 depletion in Epha2–/– mice increased kidney injury, while TREM1 levels were similar after 3 days of infection." (PMID 36138043, 2022). "Taken together, these results suggest that infection by Leishmania infantum leads to depressed TREM-1 expression on the neutrophil surface and may contribute to the inflammatory imbalance that characterizes active VL disease." (PMID 35402286, 2022). "Taken together, these results suggest that infection by Leishamina infatum alters the expression of TREM-1 on the surface of neutrophils which leads to an imbalance in the regulation of inflammatory responses, which prevents adequate defense against VL disease." (PMID 35402286, 2022). "TREM1 activation in macrophages triggers signaling pathways that positively modulate proinflammatory responses, augmenting the secretion of proinflammatory chemokines and cytokines in response to infections." (PMID 35638785, 2022). "Triggering receptor expressed on myeloid cells (TREM)-1) is a glycoprotein member of the Ig family which is upregulated during inflammation linked to infection as well as in non-infectious inflammatory conditions." (PMID 33708198, 2021). "The PPRs, IL6, and TREM1 CPs were highly induced at 24 h compared to 2 h post-infection." (PMID 33382951, 2021). "In IL-27-containing groups, several inflammation or infection-related pathways were predicted to be activated, including TREM1 signaling, pattern recognition receptors, neuroinflammation, and acute phase response, whereas inhibition of the PD1/PD-L1 cancer immunotherapy pathway was predicted." (PMID 34209203, 2021). "This implies that the TREM-1 pathway may be involved in the inflammatory cytokine response at 24 hpi during EV-D68 infection." (PMID 34887856, 2021). "Our RT-PCR results showed that TREM-1 mRNA levels were significantly induced upon EV-D68 infection." (PMID 34887856, 2021). "Additionally, it has been suggested that sTREM-1 is generated by cleavage of membrane-bound TREM-1 from the cell surface, and the infection model recruits many neutrophils that express this receptor." (PMID 34960790, 2021). "To further investigate whether EV-D68 infection influences TREM-1 expression and confirm the accuracy and reliability of the transcriptome data, we infected RD cells with EV-D68 and examined the changes in the RNA and protein levels of TREM-1." (PMID 34887856, 2021). "Small Interference RNA (siRNA) infection was used to silencing BRD4 or TREM1." (PMID 33446277, 2021). "In line with our hypothesis, TREM-1 expression at both the mRNA and protein levels were significantly higher in the livers of WT-infected mice than ΔspvB-infected mice at 3 days post-infection." (PMID 33475464, 2021).
infection (continued). "TLRs, PPRs, IL6, TREM1, and NF-κB CPs were highly activated at 24 h compared to 2 h post-infection." (PMID 33382951, 2021). "Although we could hypothesize that suppression of the TREM1 pathway may be beneficial for the pathological processes associated with IPA, our results indicate a higher susceptibility to infection by A. fumigatus." (PMID 33525982, 2021). "Mechanistically, this is the first report describing the transcriptome profiles during EV-A71 infections in primary human cells, and the potential involvement of TREM-1 in the severe disease pathogenesis, thus providing new insights for future treatment targets." (PMID 32123257, 2020). "In addition to the 27 kDa membrane receptor, TREM-1 exists as a 15~17.5 kDa soluble form in biological fluid during infection or inflammation." (PMID 32899943, 2020). "In response to in vitro infection with two clinical isolates of the LAM family of Mtb (UT127 and UT205), MoTB displayed an attenuated inflammatory mRNA profile associated with down-regulation the TREM1 signaling pathway." (PMID 32391286, 2020). "However, the intensity of TREM-1 inhibition was more pronounced in moderate isolate infection when compared to severe-infected condition." (PMID 32123257, 2020). "Moreover, membrane-anchored TREM-1 is shed by metalloproteinases as a soluble form of TREM-1, and soluble TREM-1 can be used as a potential marker for identifying clinically ill patients with infection." (PMID 32825174, 2020). "In addition, necrosis of host cells due to the infection will also provide more ligands (such as actin and HMGB1) to activate TREM-1 signaling to cause severe inflammation." (PMID 29619033, 2018). "Finally, TREM-1 expression on immune cell surfaces is known to be highly time-dependent, but also variable according to the pathogen involved and the source of infection." (PMID 27729010, 2016). "TREM-1 is a receptor that amplifies acute pro-inflammatory responses in infection." (PMID 27762264, 2016). "Therefore, TREM1 signalling, even when restricted by sTREM1, seems to produce protracted infection accompanied with increased immunopathology." (PMID 27328755, 2016). "However, at day 9, Trem1−/− mice manifested a significantly lower degree of infection, compared to wild-type mice (p < 0.05); at day 12, Trem1−/− mice had already cleared the virus, whereas wild-type mice still showed a low level of infection." (PMID 27328755, 2016). "There are conflicting reports on the role of TREM-1 in in vivo infection models." (PMID 27253382, 2016). "Upon infection with L. monocytogenes increases and decreases in gene expression were observed which were enriched for TREM1, IL-10 and Granulocyte Adhesion and diapedesis some of which are in keeping with previously reported mechanisms of protection or pathogenesis." (PMID 26918359, 2016). "Our previous study indicated that highly virulent S. suis infection could activate the TREM-1 signaling pathway, which promotes host clearance of S. suis during early infection." (PMID 26618144, 2015). "We may thus conclude that TREM-1’s function and activities may be dependent on the type of infection." (PMID 25347935, 2014). "Moreover, many receptors and adaptors are downregulated after infection with WT parasites only: Dectin-1 (Clec7a), IL-1 receptor type I, Nlrc4 and Trem1." (PMID 24736445, 2014). "It is established that TREM-1 is upregulated in infection and inflammatory tissues." (PMID 24842612, 2014). "During infection, receptor expression is modulated and soluble TREM-1 is released." (PMID 25347935, 2014). "These cells may also use Triggering Receptor Expressed on Myeloid Cells 1 (TREM1) pathway to respond to infection, as TREM1 pathway is critical for the regulation of acute inflammatory responses to microbial products." (PMID 24824797, 2014). "Thus, the use of biological markers of infection as the triggering receptor expressed on myeloid cells (TREM)-1 has been suggested to improve the accuracy of the diagnosis of VAP." (PMID 24289157, 2013).
infection (continued). "sTREM-1, as the soluble form of TREM-1, released by activated phagocytes, may be a more "direct" marker of infection." (PMID 23194114, 2012). "Increased TREM-1 expression was associated with the presence of inflammation but not infection in AP." (PMID 19442309, 2009). "Thus, the clear disparity in TREM-1 levels on the monocyte surface between CF and controls cannot be explained by an exacerbated proteolytic attack secondary to pathogen infection in CF patients." (PMID 18628981, 2008). "Therefore, we combined in vitro assays and bioinformatics tools to investigate whether TREM-1 is involved in host–virus interactions with RV and what is the impact of its activation for the infection outcome." (PMID 41156639, 2025). "Thus, the progressive cleavage of the receptor on the cell membrane following its activation could explain the involvement of TREM-1 at the early stages of infections, as we observed in the present study." (PMID 41156639, 2025). "Additionally, mice genetically deficient in TREM-1 had less severe disease in response to multiple pathogens without affecting their ability to clear the infection, resulting in similar pathogen loads." (PMID 35784361, 2022). "Interestingly, treatment with LP17 to inhibit TREM-1 inhibited viral replication and infection." (PMID 34887856, 2021). "Since pathogen recognition signals need to be controlled to prevent tissue damage, the inhibition of TREM1 signaling found in MoTB in response to infection with both clinical isolates of Mtb may be a mechanism to control the consequences of chronic inflammation associated to active TB disease." (PMID 32391286, 2020). "Importantly, TREM-1 expression levels could serve as a prognostic marker for severe EV-A71 infections in patients, and might point the way towards future therapies." (PMID 32123257, 2020). "Notably, the TREM-1 signalling pathway was most distinctive in severe EV-A71 infection." (PMID 32123257, 2020). "However, TREM-1 did influence bacterial dissemination as bacterial loads in blood and liver were significantly decreased in Trem-1/3-/- mice compared to WTs 72h after infection (P<0.01)." (PMID 27253382, 2016). "The net outcome of TREM-1 regulation in PMNs by P. gingivalis may depend on the stage of infection." (PMID 24124513, 2013). "Thus, these clear differences in TREM-1 levels at the monocyte surface could be explained by the presence of a pathogen infection in CF patients." (PMID 18628981, 2008). "During infection with human immunodeficiency type 1 (HIV-1) in macrophages, Mfn2 was up-regulated by TREM1." (PMID 35958608, 2022). "Specifically, upregulation of MAPK TREM1 and IL17 signalling pathways and downregulation of erythropoietin and cholesterol biosynthesis pathways were observed after infection with MA08." (PMID 34671358, 2021). "In contrast to studies on the deleterious roles of TREM-1 which had focused on blocking signaling, a large body of evidence suggests a beneficial role of TREM-1 agonists in bacterial clearance and infection resolution." (PMID 33767714, 2021). "This suggests that during infection or endogenous danger molecule exists, TLR serve as important contributors to RASF-mediated regulation of TREM-1 expression in monocytes, which eventually exacerbates RA inflammation." (PMID 31287012, 2019). "At 10 days after infection, HIV-infected macrophages displayed increased levels of TREM1 (P = 0.02)." (PMID 31719184, 2019). "At day 9 after infection, C57BL/6 mice still manifested VL4 positive hepatocytes; in contrast, the number of VL4 positive hepatocytes in Trem1−/− mice was negligible." (PMID 27328755, 2016). "We observed increased TREM-1 and TREM-2 expression during experimental melioidosis, both at the local site of infection and systemically." (PMID 27253382, 2016).
infection (continued). "Thus, we speculate that analogous to the divergent results obtained for endotoxin-challenged DAP12-deficient mice, possibly the infection dose, the nature of the microbial agent and/or the kinetics of the infection may be critical parameters regarding the requirement for TREM-1." (PMID 24453980, 2014). "Further studies are needed to better elucidate the functions and activities of TREM-1 and TREM-2, especially in regards to single-pathogen infection as compared to a polymicrobial-driven disease." (PMID 25347935, 2014). "Regarding the murine dataset (GSE41594), Trem1 was among the upregulated genes in infected mice in comparison to their non-infected counterparts (control) after three days of infection (log2FC of 1.842, p = 2.53513E-09)." (PMID 41156639, 2025). "Specifically, P. gingivalis at a multiplicity of infection (MOI) of 100 upregulates TREM-1 gene expression and sTREM-1 secretion without significantly altering DAP12 expression." (PMID 41226426, 2025). "The expression values of Trem1 were compared by one-way ANOVA between control and infected animals on each day of infection, with significant differences observed in the three different timepoints (Turkey’s test p < 0.0001, 0.0075, and 0.0005, for days 3, 7, and 14, respectively)." (PMID 41156639, 2025). "Many studies have analyzed the significance of TREM-1 in various diseases related to infection and non-infectious inflammation." (PMID 38541074, 2024). "Interestingly, although TREM-1-/- mice were protected after exposure to infectious agents, TREM-1/3-/- mice had worse outcomes after infection." (PMID 35784361, 2022). "Among the significantly enriched IPA canonical pathways, TREM1 and IL-10 signaling were enriched in both L. interrogans- and L. biflexa-infected BMDMs, regardless of the infection period." (PMID 35638785, 2022). "In addition, specific upregulation of the MAPK, TREM1 and IL17 signalling pathways was induced after infection with MA08." (PMID 34671358, 2021). "For this reason and in order to see the intact role of TREM1 in response to A. fumigatus infection we used from now on a non-immunosuppressed infection model." (PMID 33525982, 2021). "TREM-1 is not detectable in healthy individuals but only measured in body fluids in response to infection." (PMID 33708198, 2021). "The highly induced CPs (P < .0001) at 2 h post-infection were Neuroinflammation Signaling, TLRs, PPRs, IL6, and NF-kB Signaling; while at 24 h, the highly induced CPs (P < .0001) were TLRS, Neuroinflammation Signaling, PPRs, IL6, and TREM1 Signaling." (PMID 33382951, 2021). "However, the inhibition of the TREM1 signaling pathway in MoTB infected with Mtb could reflect an impaired recognition of the pathogen due to its previous activation in circulation, and therefore fail to activate adequate defense mechanisms that control the infection." (PMID 32391286, 2020). "Likewise, Hu and group further support the role of MyD88 protein as the point of cross talk between TREM-1 and TLR-4 signaling in the infection of corneal epithelial cells with fungi Aspergillus fumigatus." (PMID 25505454, 2014). "The aim of this study was to evaluate the utility of five markers of infection: C-reactive protein (CRP), procalcitonin (PCT), soluble triggering receptor expressed on myeloid cells-1 (sTREM-1), CD163 and high mobility group box-1 (HMGB1), as markers of SBI in severely ill Malawian children." (PMID 19675669, 2009). "• Increased TREM-1 expression on blood monocytes is an indicator of inflammation but not of infection in patients with AP." (PMID 19442309, 2009). "Our results suggest that TREM-1 expression increases in the presence of inflammation because it was higher in all patients with AP, regardless of the presence of infection." (PMID 19442309, 2009).